DNTT (DNA nucleotidylexotransferase)
Description:
Template-independent DNA polymerase which catalyzes the random addition of deoxynucleoside 5'-triphosphate to the 3'-end of a DNA initiator. One of the in vivo functions of this enzyme is the addition of nucleotides at the junction (N region) of rearranged Ig heavy chain and T-cell receptor gene segments during the maturation of B- and T-cells.
Synonyms: TDT
Tractability: Small molecule: a high-quality ligand is known. PROTAC: ubiquitination databases record sites on it; a small molecule that binds it is known.
Target class: Enzyme; Transferase
Gene: Protein-coding gene on chromosome 10 (96,304,409 to 96,338,564, forward strand). Ensembl gene ENSG00000107447.
Subcellular location: Nucleus
Subcellular location (Human Protein Atlas): Nucleoplasm; Cytosol
Gene Ontology:
Molecular function: DNA nucleotidylexotransferase activity; DNA polymerase activity; protein binding; DNA binding; DNA-directed DNA polymerase activity; nucleotidyltransferase activity
Biological process: DNA metabolic process; DNA biosynthetic process; DNA repair
Cellular component: cytosol; nucleoplasm; nucleus
Genetic constraint (gnomAD): Loss-of-function variants: 42 observed, 57.68 expected, observed/expected ratio (o/e) 0.73, 90% interval 0.57 to 0.94. The upper end of that interval is the gene's LOEUF score, 0.94, which puts it in group 3 of 6, group 1 being the genes least tolerant of losing a copy. Missense variants: 625 observed, 623.3 expected, observed/expected ratio (o/e) 1, 90% interval 0.94 to 1.07. Synonymous variants: 211 observed, 221.78 expected, observed/expected ratio (o/e) 0.95, 90% interval 0.85 to 1.07.
Homologues: Orthologues: chimpanzee DNTT (99% identical), macaque DNTT (97% identical), pig DNTT (86% identical), dog DNTT (85% identical), rat Dntt (83% identical), mouse Dntt (81% identical), guinea pig DNTT (81% identical), rabbit DNTT (76% identical), tropical clawed frog dntt (57% identical), zebrafish dntt (46% identical). Paralogues in human: POLM (40% identical), POLL (23% identical), POLB (15% identical).
Diseases named in the same sentence as DNTT in open-access papers:
DNTT is named in the same sentence as 110 diseases in open-access papers, as found by Europe PMC text mining. Sharing a sentence is not in itself a finding about the gene and the disease. The quoted sentences say what the papers report.
lymphoma (33 papers, 1979 to 2025). A malignant (clonal) proliferation of B- lymphocytes or T- lymphocytes which involves the lymph nodes, bone marrow and/or extranodal sites. "In comparison to lymphomas infected with ΔEBNA2 alone, the ΔEBNA2 + Myc tumors have much higher expression of IGLL1 (CD179B, surrogate light chain), DNTT (terminal deoxynucleotidyltransferase, TDT), RAG1 and IL7R." (PMID 38620028, 2024).
acute lymphoblastic leukemia (20 papers, 1981 to 2025). Leukemia with an acute onset, characterized by the presence of lymphoblasts in the bone marrow and the peripheral blood. "DNTT encodes terminal deoxynucleotidyl transferase (TdT), whose expression is normally restricted to immature lymphocytes in the thymus and bone marrow, but is also a frequent feature of acute lymphoid leukemias." (PMID 38166662, 2024).
hematologic malignancies (1 paper, 2021). "Although the role of DNTT (also known as TdT) in PC is unclear, it has been recognized as an important marker in hematologic malignancies." (PMID 34769200, 2021).
DNTT also shares sentences with these, for which no sentence is quoted: tumor (140 papers); cancer (27); leukemia (23); infection (17); Burkitt lymphoma (12); breast carcinoma (11); thymoma (11); lymphoblastic lymphoma (9); B-cell lymphoma (8); follicular lymphoma (8); diffuse large B-cell lymphoma (6); acute myeloid leukemia (5); Stroke (5); acute leukemia (4); B-cell neoplasm (4); gastric cancer (4); mantle cell lymphoma (4); Sepsis (4); thymic carcinoma (4); viral infection (4); diabetes (3); liver fibrosis (3); myeloid sarcoma (3); T cell lymphoma (3); acute kidney injury (2); autoimmune disease (2); Autoimmunity (2); B cell lymphoblastic leukemia (2); bladder cancer (2); cervical cancer (2).
A further 77 diseases each share a sentence with DNTT in 2 papers or fewer.